TERT (telomerase reverse transcriptase)
Diseases named in the same sentence as TERT in open-access papers (continued):
Sharing a sentence is not in itself a finding about the gene and the disease.
cancer (continued). "The main advantage of TERT is its high cancer-specific expression." (PMID 33329574, 2020). "Further understanding of how cancer cells that do not harbor the TERT mutation activate TERT through various regulatory methods still needs to be elucidated." (PMID 32849278, 2020). "TERT activity is detected in up to 90% of human primary cancer." (PMID 33317554, 2020). "We report that disruption of TERT severely compromises cancer cell survival in vitro and in vivo." (PMID 31963842, 2020). "Considering the hypermethylation of the distal TERT promoter around cg11625005, which serves as a biomarker for identification and prognosis of cancer cells, it could contribute positively to gene expression." (PMID 33245585, 2020). "The exact mechanisms of TERT upregulation in those cancers remain largely unclear." (PMID 33061812, 2020). "The dual gRNA approach for removing TERT E4 presented here may prove to be an effective and safe method for gene editing therapy targeting telomerase in cancer cells." (PMID 31963842, 2020). "Numerous studies have revealed an intimate association between the variants of the TERT or TERC gene and susceptibility to cancer, aging-associated disorders and many other pathological conditions, however, their relationship with primary GN/CKD/ESRD has never been explored." (PMID 32366311, 2020). "Thus, extension of lifespan by TERT-overexpression is only possible in the context of a cancer-resistant background." (PMID 32253367, 2020). "Therefore, more work remains to be done before TERT implications in cancer can be fully comprehended." (PMID 32599885, 2020). "We analyzed genomic DNA from cancer cell lines that were heterozygous for the TERT exon 2 SNP." (PMID 33245585, 2020). "Although further study is necessary, the regulation of TERT by HMGA2 might play a role in cancers that have disrupted TGF-β pathways, including HCC." (PMID 32577156, 2020). "In general, we observed that immortalized and cancer cell lines were hypermethylated in a region upstream of the recurrent C228T and C250T TERT promoter mutations, while non-malignant primary cells were comparatively hypomethylated in this region." (PMID 32468444, 2020). "Better understanding of TERT promoter methylation patterns may enable us to decipher the different mechanisms by which TERT is reactivated in different cancer types." (PMID 33245585, 2020). "Thus, in cell lines from cancers of many different tissues, the TERT proximal promoter has canonical DNA methylation, with low methylation correlating with increased TERT expression." (PMID 33245585, 2020). "This advances rtTERT as key component of TERT-based therapeutic vaccines against cancer." (PMID 32570805, 2020). "TERT is a target of choice in antitumor strategies due to its reactivation in numerous cancers." (PMID 32204305, 2020). "The study of TERT promoter methylation has been complicated by reports of hypermethylation of the TERT promoter in cancer, seemingly contradicting the canonical model of promoter methylation causing transcriptional silencing by inhibiting transcriptional activator binding." (PMID 32920953, 2020). "However, in most cancers, TERT undergoes reactivation, and by extending telomeres (the canonical function of TERT) it contributes to cancer formation and progression." (PMID 33329574, 2020). "These phenomena gave us impetus to investigate the exact mechanisms of TERT upregulation in cancers without high frequency TERT promoter hotspot mutations." (PMID 33061812, 2020). "Therefore, we aimed to investigate the diagnostic utility of BRAF, NRAS, TERT promoter mutation, and its combination from our FNAB specimen series at Dharmais Cancer Hospital." (PMID 33247684, 2020).
cancer (continued). "Ultimately, increasing methylation of the proximal TERT promoter to decrease TERT expression may be a route to explore for cancer therapeutics." (PMID 33245585, 2020). "We plan to test this approach in application to TERT in murine cancer models." (PMID 32570805, 2020). "Nonetheless, the mechanism underlying the activation of one TMM over another still remains to be clearly elucidated, even if a genetic basis (e.g., TERT promoter mutations, ATRX mutations, telomeric variant repeats) for the activation of either mechanism in cancer is becoming recognized." (PMID 32290440, 2020). "For example, the MYC locus in SW480 cells contains 135 rearrangements in a 4-Mb genomic window, whereas a larger complex event was observed in HCC1954 cells around the similar locus, which also involved two other cancer driver genes, TERT and APC, on chromosome 5." (PMID 32024999, 2020). "Because hESCs express TERT, it seems unlikely that methylation and inactivation of repressor binding sites in this distal promoter region by themselves lead to TERT reactivation in cancer cells, as has been suggested." (PMID 33245585, 2020). "Here we applied the CRISPR/Cas9 gene editing system to target the TERT gene in cancer cells." (PMID 31963842, 2020). "Notably, the cancer cell lines investigated in this study included both cancer cells with wild type (WT) TERT promoters, and cancer cells that harbored highly recurrent TERT promoter mutations, C228T or C250T." (PMID 32468444, 2020). "The NF-κB signaling pathway is a master regulator of TERT activation in cancer cells." (PMID 33329574, 2020). "Further, a variety of high resolution techniques used to examine the TERT locus specifically, including fluorescence in situ hybridization (FISH), Southern blot, and quantitative PCR, have shown copy number amplifications of TERT in both cancer cell lines and tumors." (PMID 32849278, 2020). "In effect, the interaction between TERT and NFκB p65 may also present cancer cells with a pro-malignant feedback loop that simultaneously sustains cell proliferation, chronic inflammation, and telomerase activity." (PMID 32599885, 2020). "Expression of TERT, as assessed by RT-qPCR, confirmed low to no expression in primary and ALT-positive cancer cell models, while immortalized and telomerase-dependent, ALT-negative cancer cell lines had a comparably higher TERT expression, particularly in the TERT-immortalized cell line models." (PMID 32468444, 2020). "It is proposed that during cancer development some unknown additional event changes the alternative splicing pathway to produce full-length TERT and reestablish telomerase activity." (PMID 32674474, 2020). "Our group showed, in a study of 60 malignant tumors (PTC, FVPTC, FTC, and HCC) and 73 benign lesions, that malignant tumors showed a higher amount of the full-length isoform than the inactive TERT isoforms, while conversely, the benign tumors showed higher levels of the deletion isoforms." (PMID 32849278, 2020). "As TERT is low in abundance even in the context of cancer, some assays such as co-immunoprecipitation often require the non-physiological overexpression of its recombinant forms, which may lead to false positives." (PMID 32599885, 2020). "However, TPMs along with other genetic alterations in TERT contribute to telomerase activation only in a subset of cancers, and thus deciphering the mechanism of telomerase activation in remaining cancers remains unidentified." (PMID 32674474, 2020). "TERT is highly upregulated in embryonic stem cells, progressively dividing cells, and cancer cells." (PMID 33166332, 2020). "Except for TERT promoter mutations, most of the known non-coding mutations identified as recurrent in cancer did not associate significantly with mRNA expression level changes of target genes located nearby on the genome." (PMID 33049910, 2020).
cancer (continued). "Also targeting the TERT gene promoter, aberrant TERT promoter methylation is detected in a large number of cancers, in a region described as TERT hypermethylated oncological region (THOR)." (PMID 31941070, 2020). "We confirmed that cancer cells addicted to TERT rapidly die by suppression of hTERT." (PMID 32214089, 2020). "In cancer, different factors may influence the degree of telomerase activity, such as expression levels of TERT, TERT sub-cellular localization, or tissue origin of the lesion." (PMID 32292795, 2020). "In the present work, we hypothesize that Cas9-mediated gene KO of TERT will compromise cancer cell survivability." (PMID 31963842, 2020). "This type of fine tuning of TERT expression may account for the modest activation of TERT expression in most cancers." (PMID 32468444, 2020). "For these reasons, TERT is actually considered a central regulator of the hallmarks of cancer." (PMID 33553285, 2020). "Following telomerase activation, it is intriguing that cancer cells would repress TERT expression." (PMID 32468444, 2020). "In this work we aimed to evaluate both TERTp mutations and TERT mRNA features in a series of benign and malignant thyroid lesions, representing a series without aggressive features." (PMID 32659948, 2020). "Therefore, TERT is frequently activated in many malignant tumors and closely related to cancer progression." (PMID 32810393, 2020). "In addition to its classic role in affecting telomere length, telomerase is also related to the migration of cancer cells, and the expression of the subunit telomerase reverse transcriptase (TERT) can be used to distinguish benign from malignant tumors." (PMID 32462015, 2020). "In a survey of TERT promoter alterations in human cancers, more than 80% of them did not harbor promoter mutations." (PMID 32468444, 2020). "In addition to the canonical inhibitory effects on TA, treatment with BIBR1532 has been shown to down-regulate the expression of cMyc in a series of cancer cell lines, resulting in decreased TERT transcription." (PMID 33553285, 2020). "Moreover, we mainly explored the correlation between TERT mutation and TMB score or neoantigens load in multiple cancer types." (PMID 32810393, 2020). "Furthermore, mutations were detected in genes that are known for their involvement in other cancer types, such as TERT, KMT2D, PIK3CA, AKT1, CTNNB1 and NR1D1." (PMID 32455687, 2020). "Several TERT-based cancer vaccines are currently in clinical trials, but immune correlates of their antitumor activity remain largely unknown." (PMID 32570805, 2020). "The mechanism by which TERT promoter mutations ultimately facilitate cancer progression and can constitute prognostic factors are not fully elucidated." (PMID 32850388, 2020). "Future studies may investigate whether targeted methylation or other inhibition of the proximal E‐Box results in decreased TERT expression in cancer cells." (PMID 33245585, 2020). "This makes it unclear how the majority of cancer lines have active TERT expression." (PMID 33245585, 2020). "This raises a question whether cancer vaccine should in fact be based on the full length TERT, or rtTERT domain may be sufficient?" (PMID 32570805, 2020). "A study in 2015 of multiple cancer cell lines showed monoallelic expression of TERT in cell lines heterozygous for the TERT promoter mutation, although the study did not elucidate which allele was transcribed." (PMID 32849278, 2020). "Moreover, an association between TERT expression and KRAS mutation was shown in TAs, suggesting the development of drugs targeting this pathway for cancer prevention." (PMID 32932803, 2020). "Since the replicative potential of cancer cells is mainly attributable to the inappropriate reactivation of TERT, targeting telomerase may be a promising anticancer strategy, but it is apparently restricted to tumors with short telomeres." (PMID 32722398, 2020).
cancer (continued). "Taken together, the present work validated TERT as a good target gene, developed efficient editing strategies on this gene, and determined that TERT haploinsufficiency is a sufficient dosage to suppress cancer cell survival in vitro and in vivo." (PMID 31963842, 2020). "Altogether, monitoring of anti-TERT CD4 T cell responses in vitro could greatly help refine the stratification of cancer patients and predict clinical outcome in response to immune checkpoint blockade." (PMID 32630460, 2020). "TERT activation in cancer occurs through a variety of mechanisms." (PMID 32849278, 2020). "Most cancer cells (80–90%) activate TERT and subsequently telomerase to gain immortalization." (PMID 31963842, 2020). "Notably, TERT promoter mutations associate with epithelial-to-mesenchymal transition (EMT) gene expression signature and MAPK signaling in several cancers." (PMID 33113965, 2020). "However, Sp1 would be a weak candidate for a biomarker of cancer‐specific TERT expression because of its ubiquitous expression in normal cells." (PMID 33329574, 2020). "Overall, these findings suggest that TERT promoter hypermethylation in cancer cells may be involved in attenuating the degree of TERT activation in cancer cells." (PMID 32468444, 2020). "However, at the allele level, we find that hypermethylated alleles are associated with repressed expression, while the remaining unmethylated alleles are associated with active chromatin marks, and are responsible for the observed TERT expression in cancer." (PMID 32468444, 2020). "However, the role of TPE-OLD and its cooperation with other mechanisms in TERT activation during cancer requires further investigation." (PMID 32674474, 2020). "Alternative splicing of TERT has also been proposed to be involved in telomerase silencing during the development process and as one of the putative mechanisms involved in telomerase activation in cancer cells." (PMID 32674474, 2020). "This hypomethylation is consistent between both WT and TERT promoter‐mutant cancer cell lines." (PMID 33245585, 2020). "Nevertheless, to date, previous studies on colorectal cancer have evaluated the association of genetic TERT variants with cancer risk, but not with clinical outcome." (PMID 33113831, 2020). "Telomerase reverse transcriptase (TERT) is a very attractive target for cancer immunotherapy." (PMID 31164958, 2019). "Therefore, these mechanistic understandings of the TERT contribution to various cancer hallmarks should be helpful to the rational development of TERT-based tools for clinical diagnosis and management of cancer patients." (PMID 31284662, 2019). "However, advances in high-throughput next-generation sequencing technologies have prompted a revolution in cancer genomics, which leads to the recent discovery that genomic alterations take center stage in activating the TERT gene." (PMID 31285550, 2019). "From the therapeutic point of view, targeting the interaction between TERT and epigenetics may contribute to the development of novel anti-cancer strategies." (PMID 31284662, 2019). "The disruption of these loops or networks by targeting TERT may be a novel anti-cancer strategy and are expected to be detrimental to cancer cells." (PMID 31284662, 2019). "The hypermethylated TERT promoter has been shown unique to human cancer and might serve as a diagnostic biomarker." (PMID 31284662, 2019). "Furthermore, TERT over-expression in cancer cells leads to cellular resistance to DNMT inhibitor (DNMTi)-induced apoptosis, while its depletion sensitizes the DNMTi effect." (PMID 31284662, 2019). "This suggested that TERT expression could promote the development of spontaneous cancer in mice with wild-type (WT) telomere length." (PMID 31911897, 2019). "Telomerase reverse transcriptase (TERT, or hTERT) is a catalytic subunit of the telomerase enzyme, comprising the most important unit of the telomerase complex, and its aberrant expression has been widely reported in a variety of cancer types." (PMID 31024447, 2019).
cancer (continued). "The pioneering works in human TERT promoter-driven oncolytic adenoviruses were published in 2003, when three separate reports demonstrated that human TERT promoter-driven expression of the adenoviral E1A gene endowed cancer specificity on adenoviral replication." (PMID 31035374, 2019). "Future interesting applications of EACCD could include studying molecular markers, such as T1799A point BRAF mutation, TERT mutation, and HRAS mutation as these become available in cancer registries." (PMID 31139148, 2019). "Because EMT and CSCs are key factors promoting therapeutic resistance, aggressive diseases, metastasis and relapse in cancer, the identification of these TERT functions sheds light on its wide array of contributions to oncogenesis, which should have important biological and clinical implications." (PMID 31284662, 2019). "Telomerase reverse transcriptase promotes cancer cell proliferation by augmenting tRNA expression." (PMID 31316002, 2019). "Interestingly, two plasmids expressing the shRNA candidate with the strongest silencing effect toward either TERT or TERC (among three shRNA candidates for each target gene) showed similar cancer cell growth inhibitory effects." (PMID 31035374, 2019). "Taken together, the aberrant TERT expression and TERT promoter hypermethylation may serve as prognostic factors in multiple types of human cancer, and further evaluation including large cohorts of patients is required for future clinical application." (PMID 31284662, 2019). "Collectively, these data suggest that TERT-promoter-mutated FT-UMPs should be considered malignant tumors with a higher recurrence rate than miFTCs without TERT promoter mutations, but similar to that of TERT-promoter-mutated miFTCs." (PMID 31561592, 2019). "For some genes, such as TERT, higher levels of DNA methylation for some cancer types might represent a barrier to gene overexpression, which SSVs appear to help overcome in many cases of our patient cohort." (PMID 31610796, 2019). "Reactivation of telomerase reverse transcriptase (TERT) is an important event in cancer." (PMID 31408918, 2019). "TERT expression has been reported to be reactivated in 85% of all cancers." (PMID 32082377, 2019). "TERT expression is normally silenced in nearly all somatic cells, and a telomerase reactivation is an important factor in escape from replicative senescence, one of the hallmarks of cancer." (PMID 30967140, 2019). "In a recent study, it was reported that TERT transcript are expressed in normal cell and tissues at a level similar to the one measured in cancer cells suggesting that the major difference in telomerase activity between normal and cancer cells relies in a shift in splicing." (PMID 31911897, 2019). "Interestingly, re-expression of TERT has been shown to promote escape from OIS in BRAF-mutant cancer cells." (PMID 31391125, 2019). "The evolutionarily acquired telomerase repression as a protective strategy against cancer, together with the multiple oncogenic effects of TERT/telomerase as revealed by modern experimental approaches, have pointed to the importance of TERT/telomerase in cancer development and progression." (PMID 31285550, 2019). "Thus, it is evident from these findings that TERT contributes to the aberrant PTEN promoter methylation by up-regulating DNMT3 transcription in cancer cells." (PMID 31284662, 2019). "Importantly, stable hTERC27 expression in TERT-positive cancer cells via lentivirus attenuated tumorigenicity compared to parental cancer cells." (PMID 31035374, 2019). "In addition, TERT interacts with NF-κb p65, activating NF-κb target genes and upregulating the expression of a number of metalloproteinases (MMPs) in cancer cells." (PMID 31285550, 2019). "Whether the effects of GABPA on the wt TERT promoter and cancer development/progression are context-dependent?" (PMID 31285550, 2019).